CD34 (CD34 molecule)
Diseases named in the same sentence as CD34 in open-access papers (continued):
Sharing a sentence is not in itself a finding about the gene and the disease.
hamartoma (6 papers, 2012 to 2024). A benign and excessive tumor-like growth of mature cells and normal tissues which grow in a disorganized pattern. "Furthermore, immunochemical staining for CD34 and factor XIIIa is usually positive in the hamartoma." (PMID 23199263, 2012). "The name “plaque-like CD34-positive dermal fibroma” (PDF) was suggested for these lesions because they appeared after birth and were more like tumors than hamartomas." (PMID 34449590, 2021). "In hamartoma, apart from the presence of a bronchial epithelium, fragments of the mature cartilage can also be found, while in pulmonary hemangioma, true vascular spaces filled with blood and lined with CD31- and CD34-positive endothelial cells are present." (PMID 30691016, 2019). "Thus, immunohistochemical detection of CD34, CD99, and bcl-2 is inefficient in differentiation of hamartoma-like SFTs from pancreatic hamartomas." (PMID 26425382, 2015). "The histopathological diagnosis confirmed the original suspect of splenic hamartoma, also supported by the immunohistochemical stains positive for CD-8 and negative for CD-34." (PMID 23125940, 2012).
hyperlipidemia (6 papers, 2008 to 2024). "To further examine the effect of hyperlipidemia on CD34+ cells and CD34-lineage fibroblasts, we extracted fibroblast populations from the tdTomato+ cell single-cell dataset of these two groups and further clustered them into four subclusters." (PMID 39198543, 2024). "To summarize, our study utilized scRNA-seq of hearts from mice and humans, in addition to lineage tracing techniques, to elucidate the crucial involvement of CD34+ cells in myocardial remodeling during hyperlipidemia." (PMID 39198543, 2024). "This study aimed to explore the mechanism of CD34+ cell differentiation in cardiac fibrosis during hyperlipidemia." (PMID 39198543, 2024). "To comprehensively map the distribution of cardiac-resident CD34-lineage cells in patients with cardiac hypertrophy with hyperlipidemia, we conducted scRNA-seq on CD34-lineage cells (tdTomato+ cells)." (PMID 39198543, 2024). "To further clarify the role of hyperlipidemia in hypertrophy-induced fibrosis, we performed scRNA-seq analysis of Cd34-CreERT2; Rosa26-tdTomato&ApoE-/- and Cd34-CreERT2; Rosa26-tdTomato mice after surgery." (PMID 39198543, 2024). "After adjustment for ethnicity, hyperlipidemia, and cotinine, CAC-2 (CD31+/34+/45+), CAC-8 (CD31+/34+/45+/AC133–), and CAC-14 (CD34+/45+/AC133+) were significantly associated with t,t-MA." (PMID 28886060, 2017). "There was also a negative association between hyperlipidemia and total CD34+ progenitors in the CHF groups." (PMID 18800166, 2008). "Similarly, participants with hyperlipidaemia had 3.26-fold increase in CD34 + EPC subtype numbers." (PMID 39186241, 2024). "Through the integration of bone marrow transplantation models and lineage tracing, our study showed that hyperlipidemia can expedite the differentiation of non-bone marrow-derived CD34+ cells into fibroblasts, particularly FABP4+ fibroblasts, in response to angiotensin II." (PMID 39198543, 2024). "Consequently, these findings imply that CD34+ cells may be involved in fibrosis through their differentiation into FABP4+ fibroblasts, which distinguishes them from other cardiac fibroblasts involved in cardiac remodeling in lipid metabolism disorders (hyperlipidemia)." (PMID 39198543, 2024).
limb ischemia (6 papers, 2019 to 2026). A ischemia that involves the limb. "On the one hand, preclinical studies have demonstrated the potency of CD34 positive (CD34+) cells for therapeutic neovascularization and improved tissue perfusion and function by local delivery in myocardial and limb ischemia models." (PMID 34943815, 2021). "Also, the circulating CD34+ cell count is noteworthy because accumulating evidence supports CD34+ cells use in cell therapy for cardiac and limb ischemia in human." (PMID 31584974, 2019).
Myocardial fibrosis (6 papers, 2021 to 2025). "In the area of myocardial fibrosis, we found large numbers of tdTomato+ cells and Postn+ cells but only a small number of CD34+ cells after angiotensin II treatment compared to those in the sham group." (PMID 39198543, 2024). "Similar observations have been made in the heart, where depletion of CD34+ cells led to reduced myocardial fibrosis and improved cardiac function." (PMID 39042469, 2024). "We systematically characterized the cellular landscape of myocardial fibrosis at single-cell resolution and generated a comprehensive cell atlas encompassing CD34+ cells and fibroblasts." (PMID 39198543, 2024). "To further clarify the relationships among CD34+ cell reduction, myocardial fibrosis, TG content, and cardiac function, we conducted a series of correlation analyses and found that CD34-derived fibroblasts were significantly correlated with cardiac function." (PMID 39198543, 2024). "Then, in order to determine the origin of CD34+ cell that plays a role in myocardial fibrosis, bone marrow transplantation model was performed." (PMID 36805782, 2023). "When CD34+ cells were partially eliminated, the fibroblasts in the heart were markedly reduced, leading to a decrease in myocardial fibrosis and improving cardiac function." (PMID 36805782, 2023). "To clarify the role of End-MT in the formation of myocardial fibrosis, we further evaluated the coexpression of CD34/CD105 and α-SMA, a marker of myofibroblasts, by immunofluorescence." (PMID 36185701, 2022). "For instance, stemness-related genes such as Cd34 and Hif1a, as well as pathways involved in oxidative phosphorylation and glutathione metabolism, should be closely monitored in future efforts to prevent post-MI myocardial fibrosis." (PMID 40595870, 2025). "Taken together, results support the notion that it could be possible to target CD34+ cells directly in the treatment of myocardial fibrosis." (PMID 36805782, 2023). "Furthermore, our study provided the solid evidence that ablation of CD34+ cells can alleviate the myocardial fibrosis." (PMID 36805782, 2023). "Interestingly, partial depletion of CD34+ cells alleviated the severity of myocardial fibrosis with a significant improvement of cardiac function in Cd34-CreERT2; Rosa26-eGFP-DTA model." (PMID 36805782, 2023). "Similar to the human data, we also found that one subset of fibroblasts (Cluster 7) displayed heightened expression of several progenitor cell markers, such as Cd34, Ly6a, Pi16, and Thy118, in mice, suggesting that Cd34-high fibroblasts may have distinct functions in myocardial fibrosis." (PMID 39198543, 2024). "To further clarify the role of CD34+ cells in myocardial remodeling in response to TAC injury, we then used a CD34 cell depletion system to find out how CD34+ cells were involved in myocardial fibrosis." (PMID 36805782, 2023). "Thus, partial elimination of CD34+ cells leads to a significant reduction in FABP4+ fibroblasts within the heart, resulting in decreased TG content, reduced myocardial fibrosis, and improved cardiac function." (PMID 39198543, 2024). "We found that fibroblasts were mainly derived from the differentiation of CD34+ cells rather than from their own proliferation during myocardial fibrosis." (PMID 39198543, 2024). "Importantly, to further clarify the differentiation process of CD34+ cells into fibroblasts rather than the proliferation of CD34+ cells in myocardial fibrosis, we constructed CD34Dre, PostnCreERT2, and R26-RSR-LSL-TdT dual-recombinase-activated lineage tracing mice." (PMID 39198543, 2024).
nodular fasciitis (6 papers, 2010 to 2025). A self-limiting, rapidly growing, non-encapsulated benign neoplasm that arises from the soft tissues. "Although in both myxoid and fibrosarcomatous areas of DFSP can both show loss of CD34 staining, the overall pattern of our patient's spindle cell proliferation in her final margin was more consistent with nodular fasciitis." (PMID 28018683, 2016).
ovarian tumors (6 papers, 1998 to 2021). "However, CD45+CD34+ cells in human ovarian tumors reportedly share monocyte and endothelial cell phenotypic characteristics and also have the ability to generate blood vessels in vivo." (PMID 24731246, 2014). "Microvessel density of benign, borderline and malignant ovarian tumours was studied immunohistochemically using antibodies to the endothelial cell markers CD31, CD34 and factor VIII-related antigen." (PMID 9649134, 1998).
perineurioma (6 papers, 2014 to 2025). A usually benign perineurioma not associated with a nerve, arising from the soft tissues. "Like intraneural perineurioma, soft tissue perineurioma is stained with EMA and GLUT1; variable immunoreactivity has been documented for CD34, α-smooth muscle actin, and pancytokeratins." (PMID 35741273, 2022). "Based on previous research, immunohistochemical staining for perineurioma cells was performed using EMA, S-100, CD34, and SMA." (PMID 24410763, 2014). "Perineuriomas are typically immunoreactive for EMA, GLUT1, CD34, and claudin-1." (PMID 39925503, 2025).
periodontitis (6 papers, 2019 to 2025). An acute or chronic inflammatory process that affects the tissues that surround and support the teeth. "CD34, analyzed with eight instrumental SNPs, showed a positive causal effect (OR = 0.237, 95% CI: 0.047–0.427, p=0.014), indicating that higher CD34 expression may contribute to elevated periodontitis risk." (PMID 41333919, 2025). "The corresponding results revealed that, compared to control samples, IGKV2D-30 and CD34 were downregulated in patients with periodontitis, while GPX2, GSTA4, and NYNRIN were upregulated in patients with periodontitis." (PMID 41333919, 2025). "These genes have been previously implicated in oxidative stress (GPX2 and GSTA4), immune regulation (CD34 and IGKV2D-30), and RNA processing (NYNRIN), which are all biologically relevant to the inflammatory and immune mechanisms underlying periodontitis." (PMID 41333919, 2025). "Simultaneously, some studies have found a reduced number of CD34-positive stem cells in the gingival tissue of periodontitis patients." (PMID 41333919, 2025). "More specifically, the authors found lower levels of CD34+ and KDR+ in patients with moderate to severe periodontitis and an inverse association with high CRP levels and EPCs, supporting the evidence of a two-way relationship between periodontitis and CVD." (PMID 31817862, 2019). "Significantly increased CD34+ cells (red) were observed in the periodontitis group." (PMID 36193890, 2022). "The biological functions and mechanistic roles of the predicted genes—such as GPX2, CD34, and GSTA4—in the pathogenesis of periodontitis remain to be empirically confirmed." (PMID 41333919, 2025). "CD34 expressing newly formed blood vessels were observed in PAPT of wildtype and anti-Act1 periodontitis mice." (PMID 33748112, 2021). "In patients with periodontitis, the expression of IGKV2D-30 and CD34 is downregulated." (PMID 41333919, 2025). "(f) Telocytes (CD34+, CD31-) express a proliferation marker, Ki67 in periodontitis." (PMID 36193890, 2022). "In this study, we use CD34+/CD31- to identify PDL-resident telocytes combined with genetic lineage tracing and Sc-RNA sequencing to determine the role of telocytes in homeostasis and periodontitis." (PMID 36193890, 2022).
phyllodes tumor (6 papers, 2014 to 2024). A benign, borderline, or malignant fibroepithelial neoplasm arising from the breast and rarely the prostate gland. "The expression of CD34 and Bcl-2, which is generally seen in malignant phyllodes tumors and periductal stromal sarcomas, has not been observed in this case." (PMID 25309767, 2014). "IHC may show expression of CD10, but phyllodes tumors generally express CD34 and B-cell lymphoma 2 (bcl-2) and do not express cyclin D1." (PMID 39474112, 2024). "CD34 and CD117, which can be positive in phyllodes tumor up to 75% and 35%, respectively, were negative in the vulvar mass as well as the primary breast phyllodes tumor." (PMID 25960902, 2015).
pituitary adenomas (6 papers, 2014 to 2025). "In the current study, we found that Gremlin is strongly expressed in pituitary adenoma tissues and that the expression level was significantly associated with CD34-positive vessels." (PMID 25834571, 2015). "The purpose of this study was to clarify the expression pattern of endocan in pituitary adenomas and explore the association between endocan expression, CD34/CD105-MVD, and radiological Knosp grades to further assess the physiological role of endocan in pituitary tumor invasion." (PMID 26809958, 2016). "Thus, they concluded that a significant relationship exists between endocan expression, Knosp tumor grades, and CD34-positive vessels of pituitary adenomas; however, we were unable to find any significant association between the presence of CD34- or CD105-MVDs and Knosp tumor grades." (PMID 26809958, 2016). "CD34 regulates angiogenesis in human pituitary adenomas and is overexpressed in aggressive pituitary tumors." (PMID 41017273, 2025). "Endocan is exclusively expressed by CD34-positive vascular endothelial cells in pituitary adenomas, where it strongly correlates with an invasive phenotype." (PMID 26809958, 2016). "In previous investigations, several angiogenic factors or biomarkers—including CD34, endocan, and vascular endothelial growth factor (VEGF)—were found to be widely expressed in pituitary adenomas and associated with an aggressive phenotype." (PMID 26809958, 2016). "Normal pituitary seemed to exhibit lower endocan expression and contained more CD34/CD105-MVDs than pituitary adenomas." (PMID 26809958, 2016). "We found that endocan protein expression was mainly detected in the tumor cells of pituitary adenomas and was significantly correlated with Knosp grades when compared to that of CD34/CD105-positive MVDs." (PMID 26809958, 2016). "Double fluorescence immunohistochemistry of Gremlin and CD34 was performed in pituitary adenoma tissues obtained during transsphenoidal surgery in 45 cases (7 PRLoma, 17 GHoma, 2 ACTHoma, and 2 TSHoma)." (PMID 25834571, 2015). "Gremlin and microvascular density (MVD) were detected by double-immunofluorescence microscopy in CD34-positive vessels from tissue microarray analysis of 60 cases of pituitary adenomas (6 PRLoma, 23 GHoma, 22 NFoma, 5 ACTHoma, and 4 TSHoma)." (PMID 25834571, 2015). "The high level of expression of Gremlin in pituitary adenoma tissue with many CD34-positive vessels and the strong coherence of these regions indicate that Gremlin is associated with angiogenesis in pituitary adenoma cells." (PMID 25834571, 2015). "Stromal cell-derived factor-1 (SDF-1) is reported to be related to MVD in pituitary adenoma as a CD34-positive endothelial progenitor cell homing factor." (PMID 25431591, 2014). "Recent evidence indicates that CD44, CD34, PTTG, FGFR4, MMP9, E‐Cadherin, and N‐Cadherin serve as biomarkers of aggressive pituitary adenomas." (PMID 41017273, 2025). "In the present study, we examined the expression of endocan, the pan-endothelial marker CD34, and the activated endothelial marker CD105 in pituitary adenomas and normal pituitary glands using semi-quantitative immunohistochemical staining." (PMID 26809958, 2016). "Our purpose is to assess the impact of endocan (endothelial cell specific molecule-1, ESM-1), CD34 and CD105 on pituitary adenoma invasion." (PMID 26809958, 2016). "Yunoue with colleagues identified cell population in pituitary adenomas that coexpressed CD133 and CD34." (PMID 27340409, 2016). "Neither Gremlin nor CD34 expression showed a significant relationship with tumor subtypes, Knosp score (evaluation score of the degree of infiltration into the cavernous sinus of pituitary adenoma), tumor size, sex, or age (data not shown)." (PMID 25834571, 2015). "Consistent with this fact, we also found that the mean positive MVDs of CD34 and CD105 in the five normal pituitary glands were markedly higher than those in pituitary adenomas, regardless of the Knosp tumor grade." (PMID 26809958, 2016).
pituitary adenomas (continued). "Endocan overexpression in TCs more accurately reflects invasiveness compared to that of CD34/CD105-MVDs and that angiogenesis may not be the primary driver of endocan-medicated pituitary adenoma invasion." (PMID 26809958, 2016).
pleomorphic xanthoastrocytoma (6 papers, 2018 to 2025). A WHO grade ll astrocytic tumor with a relatively favorable prognosis. "An improved outcome in CD34-positive tumors has been described, with GG and pleomorphic xanthoastrocytoma being the histologic types with the strongest association with CD34-positivity compared with DNETs." (PMID 36233759, 2022).
rhabdomyosarcoma (6 papers, 2012 to 2025). A rare aggressive malignant mesenchymal neoplasm arising from skeletal muscle. "Compared with the highly susceptible rhabdomyosarcoma (RD) cells, the proportions of CD34+-ECs infected with EV-A71 were 5- to 13.2-fold lower than those of infected RD cells." (PMID 38752731, 2024).
sarcomatoid carcinoma (6 papers, 2014 to 2025). A malignant epithelial neoplasm characterized by the presence of spindle cells and anaplastic morphologic features. "Sarcomatoid carcinoma typically shows positive immunoreactivity for cytokeratin and vimentin and negative immunoreactivity for S100 and CD34." (PMID 39211661, 2024).
triple-negative breast carcinoma (6 papers, 2020 to 2025). An invasive breast carcinoma which is negative for expression of estrogen receptor (ER), progesterone receptor (PR), and human epidermal growth factor receptor 2 (HER2). "Of interest, YM155 was also found by an independent team to sensitize other triple-negative breast cancer cell lines to CD34+ cells engineered to express TRAIL on their cell surfaces." (PMID 32708048, 2020). "Similarly, in humanized mice engrafted with human CD34+ cells from donors with v1/v2 SIRPA genotype bearing MDA-MB-231 triple negative breast cancer (TNBC) tumors, AB21 significantly decreased antitumor activity while clone HEF-LB had no impact on tumor growth." (PMID 33256806, 2020). "To further explore the anti-tumor HLX10 comparability to approved Pembrolizumab (Keytruda®), we used triple-negative breast cancer (TNBC) MDA-MD-231 model, which was orthotopically implanted in the humanized CD34+ (hu-CD34) NSGTM mice." (PMID 34972111, 2021). "Humanized NSG female mice (Hu-CD34+ NSG-SGM3) engrafted in their flanks with MDA-MB-231-Luc triple-negative breast cancer (TNBC) cells were transduced with MB/OVs, with or without adjuvant Pembrolizumab treatment, and tumor sizes and tumor necrosis were assessed." (PMID 39769460, 2024).
allergic asthma (5 papers, 2012 to 2025). A asthma with a basis in a pathological type I hypersensitivity reaction. "Moreover, CD34+ cells producing IL-5 and IL-13 are detected in the sputum of individuals with allergic asthma." (PMID 24822215, 2014). "CD34 plays a key role in mast cell migration and development of allergic asthma, so we hypothesized that Cd34−/− mice would also be protected from PIA." (PMID 22935073, 2012).